PSME1 (proteasome activator subunit 1)
Diseases named in the same sentence as PSME1 in open-access papers (continued):
Sharing a sentence is not in itself a finding about the gene and the disease.
tumor (23 papers, 2013 to 2025). "This demonstrated that PSME1 was progressively upregulated with disease progression, suggesting that PA28α is associated with MM cell transformation and tumor progression." (PMID 33318477, 2020). "In ovarian cancer, the C-terminal fragment of PA28 (PA28S or Reg-alpha, encoded by the PSME1 gene) was found in tumor biopsies with its presence correlated with poorer overall survival in patients, and was designated as a reliable biomarker to monitor tumor relapses and treatment." (PMID 34944095, 2021). "Interestingly, we also detected alterations in the expression of STAT1 and proteosomal proteins; however, we found very low levels of STAT1 and decreased proteosomal proteins (PSME1/2) in the Inf/FMX variant which is associated with a high incidence of tumor recurrence and nodal metastasis." (PMID 29225558, 2017). "Survival analysis of these genes in tumour samples identified seven genes that were associated with prognosis, including ACSL5, HSD17B11, CCL5, NCF2, PSME1, ACTB, and CYBB." (PMID 40299520, 2025). "As for the proteasomal enzymes, proteomic data indicated that PSME1 is a potential tumor marker in different human tumors." (PMID 38607010, 2024). "The results showed that G Protein Subunit Alpha I2 (GNAI2) was elevated in tumor samples at the mRNA level, whereas the PSME1 mRNA expression level was significantly reduced in tumor tissues." (PMID 36671532, 2023). "Although, the exact role of PSME1 in the tumor progression and its possible role in UBC immunotherapy has not yet been assessed." (PMID 37501157, 2023). "PSME1 (or PA28A) encodes a subunit of the proteasome system, which is a major source for generation of tumor antigens presented by MHC class I molecules." (PMID 27733900, 2016). "PSME1 is involved in immunoproteasome assembly for generating tumor antigens presented by MHC class I molecules." (PMID 27733900, 2016). "Furthermore, a study recently reported that PSME1 is significantly up-regulated in OSCC tumor tissues and cell lines and that it is involved in OSCC oncogenesis, with high PSME1expression significantly associated with recurrence and worse OS." (PMID 34650966, 2021). "Moreover, GC patients with high PSME1 and PSME2 expression have higher immunophenoscore and tumor mutational burden." (PMID 34650966, 2021). "Both chemotherapy and TNF-alpha may induce a local inflammatory reaction within the tumor microenvironment and therefore may influence expression of PSME1." (PMID 27733900, 2016). "While our study established associations between LMP2, PSME1, PSME2 expression (via transcriptomic/database analysis and IHC in a clinical cohort) and NACI response/survival outcomes, the IHC correlations do not establish a causal role for these immunoproteasome subunits in anti-tumor immunity." (PMID 41035633, 2025). "Notably, PSME1 is overexpressed in IDC and associated with better prognoses, which we believe may be related to genes that play different roles in tumor initiation and progression." (PMID 36671532, 2023). "Tumor samples were collected from the patients before receiving NACI treatment, and the Intratumoral proportion and expression intensity of LMP2, PSME1 and PSME2 was evaluated by performing IHC." (PMID 41035633, 2025). "In this study, we examined the expression of LMP2, PSME1, and PSME2 in pre-treatment NACI-NSCLC tumor tissue specimens and explored their prognostic value in patients with NACI-NSCLC." (PMID 41035633, 2025). "We performed IHC to examine the expression levels of LMP2, PSME1 and PSME2 in NACI-NSCLC tumor tissue samples before NACI, and to explore their prognostic value in patients with NACI-NSCLC." (PMID 41035633, 2025). "Protein expression of LMP2, PSME1, and PSME2 was assessed by immunohistochemistry (IHC) in pre-treatment tumor biopsies from a retrospective cohort of 50 resectable NSCLC patients treated with NACI (platinum-based chemotherapy + anti-PD-1/PD-L1)." (PMID 41035633, 2025).
tumor (continued). "Since our analysis above revealed that LMP2, PSME1 and PSME2 might play a role in antitumor immunity, we established a retrospective tumor cohort (validation cohort) of 50 patients with NSCLC treated with NACI to further examine our findings." (PMID 41035633, 2025). "In addition, tumor vessels density and expression of some proteasome structural subunits (PSMA4, PSMD4, PSME1) and ubiquitin were evaluated." (PMID 34561494, 2021). "The heatmap showed that 12 tumor suppressors formed into two clusters: cluster 1 contains seven downregulated tumor suppressors including PTEN, PSME1, DNAJB1, HSPH1, DEDD2, PAK1IP1, and MIR1244-3; and cluster 2 contains five upregulated tumor suppressors (OSGIN1, IFI27L1, MTCH2, NKD2, and IBTK)." (PMID 34571936, 2021). "Consistent with previous reports, our findings indicated that PSME1 was up-regulated in GC tumor tissues compared to non-cancerous tissues." (PMID 34650966, 2021). "The results show that the low expression of LMP2, PSME1, and PSME2 within the tumor is significantly correlated with a good pathological response (MPR) of patients to NACI, suggesting that they may influence treatment sensitivity by regulating antigen presentation and the immune microenvironment." (PMID 41035633, 2025). "Finally, with a deeper understanding of the molecular mechanisms underlying the formation, function, and therapeutic benefits of LMP2, PSME1, and PSME2 in the tumor, it may help guide NACI’s strategies for personalized precision medicine in the future." (PMID 41035633, 2025).
cancer (16 papers, 2012 to 2025). A tumor composed of atypical neoplastic, often pleomorphic cells that invade other tissues. "Unexpectedly, PSME1 expression, which encodes for the α subunit of PA28, was high in DMSO-treated cancer cells and very low in Bortezomib-treated cells." (PMID 34561494, 2021). "Furthermore, PSMB8-10 (PSM class I) expression was also strongly correlated with PSME1-2 (PSM class III) in 27 cancer types, e.g. BRCA." (PMID 36123629, 2022). "Interestingly, PSMB8-10 and PSME1-2 genes had a significant impact on OS in most cancer types, primarily when underexpressed." (PMID 36123629, 2022). "Additionally, high PSME1 expression was positively correlated with the infiltration of most immune cells and activation of anti-cancer immunity cycle steps." (PMID 34650966, 2021). "We found that low intratumor LMP2, PSME1 and PSME2 expression predicted a good response to NACI in cancer patients." (PMID 41035633, 2025). "We further analyzed the expression of proteins LMP2, PSME1, and PSME2 in cancer and normal tissues, involving pathological staging." (PMID 41035633, 2025). "The expression of PSME1 and PSME2 was positively correlated with the infiltration of most immune cells and the activation of anti-cancer immunity cycle steps." (PMID 34650966, 2021). "Similar to PSME1, our study found that the expression of PSME2 was positively correlated with the infiltration of most immune cells and the activation of anti-cancer immunity cycle steps." (PMID 34650966, 2021). "Gene Ontology (GO) and Kyoto Encyclopedia of Genes and Genomes (KEGG) analyses revealed that the top upregulated genes (start vs. end) in cancer‐pre cells (Curve1 and Curve2) were enriched in antigen processing and presentation pathways, such as CD74, HLA‐DRB1, HLA‐DRA, PSME1/2, and CTSB." (PMID 40860436, 2025). "Therefore, we conclude that low intratumoral expression of LMP2, PSME1 and PSME2 predicts a good response to NACI in cancer patients." (PMID 41035633, 2025). "In this study, we first demonstrated the relationship among PSMB8, PSMB9, PSMB10, PSME1, PSME2, and IRF1 in the immune micro-environment and immune score through TCGA whole cancer cohorts, and further, we proved the correlation between PSMB8, PSMB9, PSMB10, PSME1, PSME2, IRF1, and immune cells." (PMID 36700205, 2022). "In conclusion, the comprehensive pan-cancer analysis presented here demonstrated that several PSM genes (e.g. PSMA1, PSMB4-5, PSMB8-10, PSMD2, PSMD4, PSMD11, PSME1-3, and PSMG3) may be putative biomarkers for determining prognosis and choice of treatment for different cancer types." (PMID 36123629, 2022).
infection (6 papers, 2017 to 2025). The state of being infected such as from the introduction of a foreign agent such as serum, vaccine, antigenic substance or organism. "In patients with poor outcome and infection, PSME1, MTREX, and H2B1C were more abundant in T cell-derived EVs; COHA1 was less abundant in B cell-derived EVs; and PCSK9 and CMC1 were less abundant in the monocyte-derived EVs." (PMID 41345658, 2025). "Our results suggest PSME1 is one of the mediators of the proapoptotic signature of T cell-derived EVs after infection." (PMID 41345658, 2025). "Taken together, these findings indicated that PSME1 plays an equally potentially essential role in the infection system of HBV." (PMID 39281837, 2024). "We used two independent short hairpin RNAs to regulate the expression of the PSME1 gene by RNA interference in the HepG2-NTCP infection system." (PMID 39281837, 2024). "We infected Psme1/2-/- mice with a 1:1 mixture of L. pneumophila ΔΔ (pEV) and ΔflaA and calculated competitive index values from lung homogenates at 48 h post-infection." (PMID 37347796, 2023). "In blood neutrophils, in the steady state (e.g. Myc, H2-DMb2, H2-M3, H2-Q7...) but also during infection e.g. Cxcl10, H2-D1, C4a, Psme1, Stat1, Psme2, more genes were upregulated in neutrophils from female mice." (PMID 38179044, 2023). "At 8h post-infection, there was a modest but statistically significant decrease in TNF secretion from Psme1/2-/- BMDMs infected with L. pneumophila ΔΔ (plegC4) (P = 0.049) but no other PA28αβ-mediated differences were observed." (PMID 37347796, 2023).
heart disease (1 paper, 2024). "Moreover, the inhibition of PSME1 expression by vitamin B12 may also elevate the risk of death caused by heart disease (Mediated Effect=0.054, 95% CI: 0.053–0.055; Mediated Proportion=14.39%, 95% CI: 14.05%-14.74%)." (PMID 39691718, 2024).
PSME1 also shares sentences with these, for which no sentence is quoted: influenza (3 papers); diabetes (2); esophageal squamous cell carcinoma (2); myxofibrosarcoma (2); oral cancer (2); oral squamous cell carcinoma (2); retinal degeneration (2); bacterial infection (1); bladder cancer (1); breast tumor (1); Burkitt lymphoma (1); cardiomyopathy (1); cervical carcinoma (1); chronic hepatitis B (1); Cirrhosis (1); clear cell renal cell carcinoma (1); depression (1); endometrial cancer (1); epilepsy (1); gastric cancer (1); heart failure (1); hepatocellular carcinoma (1); kidney cancer (1); lymph node metastasis (1); malignant skin tumors (1); metastatic melanoma (1); monoclonal gammopathy of undetermined significance (1); myelodysplastic syndrome (1); myocarditis (1); pleomorphic liposarcoma (1).
A further 9 diseases each share a sentence with PSME1 in 1 paper.